BRAF (B-Raf proto-oncogene, serine/threonine kinase)
Diseases named in the same sentence as BRAF in open-access papers (continued):
Sharing a sentence is not in itself a finding about the gene and the disease.
melanoma (continued). "In melanoma, the use of BRAF/MEK inhibitors, depending on the driver mutations of the tumors, showed an OS of over 9 months in BRAF mutant tumors." (PMID 33520112, 2021). "Inhibition of both ERK1/2 and ERK5 has been found to be necessary for efficient targeting of neuroblastoma rat sarcoma (NRAS) and BRAF-mutant melanomas." (PMID 33572742, 2021). "To investigate the disease-associated miRNA targetome, we have applied modified cross-linking ligation and sequencing of hybrids (qCLASH) to BRAF-mutant melanoma cells." (PMID 33806450, 2021). "Surprisingly, little is known regarding the relationship between BRAF mutations and TLS presence in melanoma, although patients have benefited from anti-BRAF targeted therapies for nearly ten years." (PMID 34276690, 2021). "In 2011, a major discovery was made within another chemotherapeutic research initiative: vemurafenib, a fragment-derived BRAF protein kinase inhibitor, was approved as a cancer treatment for BRAF-mutant melanoma." (PMID 34065872, 2021). "We here show that PERK plays a critical role in BRAF inhibitor-acquired resistance in melanoma with impaired PTEN." (PMID 34282258, 2021). "We collected information on the mutation status of BRAF, NRAS and NF1 genes for SKCM TCGA samples and investigated the association between isomiR expression and the most clinically relevant mutations in melanoma." (PMID 34698264, 2021). "Specifically, it was showed to induce resistance across four human melanoma cell lines to BRAF inhibitor PLX4720, which is the progenitor compound of FDA-approved BRAF inhibitor Vemurafenib (PLX4032)." (PMID 33527896, 2021). "Cobimetinib is another MEK inhibitor developed for the treatment of advanced melanoma in combination with the BRAF inhibitor vemurafenib." (PMID 33804800, 2021). "In mucosal melanomas, apart from driver mutations affecting the MAPK pathway (e.g., NRAS, BRAF, NF1, and KIT), mutations in CTNNB1 affecting Wnt/β-catenin pathway activation have also been reported." (PMID 34149718, 2021). "Next, we show that intratumoural delivery of ES2 plus a BRAF inhibitor results in a significant increase in apoptosis and a survival advantage in mouse models of melanoma." (PMID 34689087, 2021). "Expression of the transcription factor, forkhead box D3 (FOXD3), in human melanoma cell lines, is induced during blockage of the BRAF/MEK/ERK pathway leading to upregulation of ERBB3 and activation of Akt signaling, which promotes melanoma progression." (PMID 34067095, 2021). "Studies carried out in vitro and in a mouse model have shown that BRAF inhibitors enhance the effects of IFN-α on BRAFV600E melanoma cells through the inhibition of ERK." (PMID 33407577, 2021). "In melanoma, multiple mechanisms of resistance to BRAF and MAP2K1/2 inhibition, including MAPK1/3 reactivation and PI3K-AKT1 pathway activation, converge upon MYC as a key element." (PMID 34831420, 2021). "Although inhibitors of mutant BRAF, such as vemurafenib, have led to remarkable responses in patients with melanoma, the duration of response is short-lived at 6–9 months." (PMID 33613844, 2021). "The investigated patient population only included melanoma patients for whom correct determination of the BRAF status is of utmost importance for rapid treatment stratification." (PMID 33915880, 2021). "This resistance was reversed upon dual inhibition of RAF and MET, suggesting the possibility of dual treatment options for certain BRAF-mutant melanomas refractory to single therapy." (PMID 33808627, 2021). "On the other hand, we noted relatively low tumor-plasma concordance for non-BRAF genetic alterations (28%) as compared with other studies, including the one performed in melanoma samples using the same platform (the Ion Torrent)." (PMID 34356096, 2021). "Based on the pattern of mutated genes, a genomic classification of melanoma has been established and melanomas have been classified into four subtypes: mutant BRAF, mutant RAS, mutant NF1, and Triple-WT (wild-type)." (PMID 34698264, 2021).
melanoma (continued). "Usp9x KD blocked the induction of SOX2 by vemurafenib or MEKi treatment in melanoma cell lines with mutant BRAF, A375, SK-Mel28 and wild type BRAF, SK-Mel147." (PMID 33613844, 2021). "Patients with BRAF mutant melanoma had improved median OS when they were treated with immunotherapy in the first line as opposed to targeted therapy (median OS not reached for immunotherapy versus 17.4 months with targeted treatment)." (PMID 34677256, 2021). "CTC characterization can reveal the early response to immune checkpoint inhibitors in melanoma and identify genetic heterogeneity in BRAF V600 status." (PMID 33731038, 2021). "Dabrafenib, a BRAF inhibitor, is employed in specific BRAFV600E-mutated metastatic or advanced melanoma patients." (PMID 35003391, 2021). "This study reports the survival, efficacy and safety data obtained in 382 patients with advanced BRAF V600 mutant melanoma who received TT in a real-world setting in Russia." (PMID 34064013, 2021). "Although there is comprehensive and increasing evidence about the clinical efficacy and outcomes of randomized controlled trials in patients with advanced BRAF mutant melanoma, real-word data on treatment patterns and clinical outcomes are rather scarce." (PMID 34064013, 2021). "In BRAF V600E–mutant melanoma, MEK inhibition was shown to activate caspase-3 through BIM-EL and BMF-mediated mitochondrial depolarization, which leads to apoptosis in the tumor cells." (PMID 34578339, 2021). "This technology has been successfully used for differentiating between BRAF and its wild type gene in melanoma patients." (PMID 34109155, 2021). "Since 2011, checkpoint inhibitors and BRAF/MEK targeted therapy have revolutionized the treatment of melanoma, resulting in dramatically enhanced survival." (PMID 33804910, 2021). "Recently, a number of approaches have been implemented for melanoma treatment to provide beneficial effects, including anti-programed death-1 antibodies, BRAF and MEK inhibitors." (PMID 34926249, 2021). "Although PD-1 blockade was effective regardless of the patient’s BRAF mutation status in some trials, existing data demonstrated an ORR of 15% in Chinese BRAF V600-mutant melanoma patients treated with pembrolizumab." (PMID 34504796, 2021). "CTCs are present even in the early stage of melanoma, and the number of CTCs seems to reflect patients’ responses to BRAF/MEK inhibitor treatment." (PMID 33731038, 2021). "In 2018, the combination of dabrafenib/trametinib was approved by the FDA as adjuvant treatment for BRAF V600E-mutated, stage III melanoma after surgical resection." (PMID 34771633, 2021). "A significant advance in treating melanomas harboring a mutant version of BRAF was the discovery of targeted therapy based on MAPK signaling pathway inhibitors." (PMID 34680379, 2021). "Sequential tumor biopsies obtained before and during BRAF/MEK inhibitor treatment of four (n = 4) melanoma patients were analyzed." (PMID 33275172, 2021). "Identifying which human melanoma subtypes (e.g., BRAF, NRAS, c-KIT, etc) in which an interface cell state is found awaits larger datasets of freshly isolated tumors subjected to scRNA-seq and/or SRT." (PMID 34725363, 2021). "We report a case of rapidly changing serous retinal detachment (SRD) during melanoma therapy with a combination of encorafenib, a serine/threonine-protein kinase B-Raf (BRAF) inhibitor, and binimetinib, a mitogen-activated protein kinase (MEK) inhibitor." (PMID 35070538, 2021). "Inhibition of PERK by either shRNA or a pharmacological inhibitor blocked the growth of BRAF inhibitor-resistant melanoma with impaired PTEN in vitro and in vivo, suggesting an effective approach against melanomas with mutant BRAF and PTEN deficiency." (PMID 34282258, 2021). "The combination of CCND1 amplification and CDKN2A loss or CDK4/6 mutations has been associated with resistance mechanisms and shorter progression free survival in patients with BRAF-driven melanoma treated with BRAFi." (PMID 34066022, 2021).
melanoma (continued). "The effects of BRAF inhibitors such as vemurafenib in melanoma treatment raised some expectations for the treatment of colon cancer patients." (PMID 34885128, 2021). "Several targeted therapies have been developed toward oncogenic BRAF in malignant melanoma that significantly improve PFS, but resistance often develops." (PMID 34066966, 2021). "The Cancer Genome Atlas (TCGA) classified cutaneous melanomas into four molecular subtypes: BRAF-mutant (47.5%), RAS-mutant (29%), NF1-mutant (9%), and triple-wild type (14.5%)." (PMID 34331013, 2021). "One study has shown synergistic effects of CRM1 and BRAF inhibitor combinations with effective tumor regression in BRAF-mutant melanoma." (PMID 33578751, 2021). "Mutant BRAF (v-Raf murine sarcoma viral oncogene homolog B1) inhibitors such as vemurafenib and dabrafenib have achieved unprecedented clinical responses in the treatment of melanomas." (PMID 33909629, 2021). "In this study, we aimed to investigate the outcomes of adjuvant RT on local and regional LN control along with other clinical outcomes in patients with BRAF+ and BRAF− melanoma." (PMID 34537078, 2021). "The discovery of BRAF overactivation as a common denominator in most melanomas led to the development of BRAF inhibitors (vemurafenib and dabrafenib)." (PMID 34831420, 2021). "Activating mutations of BRAF serine/threonine kinase (40–50%) and G protein NRAS (15–20%) are the main aberrations leading to the MAPK pathway activation in melanomas." (PMID 34203771, 2021). "Our group has analyzed the transcriptomes of 92 single cells cultured from a patient biopsy of a BRAF wild type/NRAS wild type melanoma metastasis by scRNA-seq." (PMID 33535416, 2021). "Although recent studies have shown that melanoma cell lines with inactivated PTEN can be growth-arrested by BRAF and MEK inhibitor treatments, they are resistant to apoptosis induction." (PMID 34282258, 2021). "Drugs targeting mutated BRAF (e.g., vemurafenib/PLX4032) in melanoma have improved patients’ survival." (PMID 34702444, 2021). "In summary, we report a novel facet of the immune-stimulatory effects of BRAF/MEK inhibition on adaptive immune responses in melanoma." (PMID 33275172, 2021). "Based on these findings, IMspire 170, a phase 3 trial, randomized 446 patients with unresectable stage III/IV BRAF-wildtype melanoma to receive either the MEK inhibitor cobimetinib plus atezolizumab, or the anti-PD-1 monoclonal antibody pembrolizumab alone." (PMID 33804800, 2021). "Hyperactivation of the MAPK signaling pathway motivates the clinical use of MAPK inhibitors for BRAF-mutant melanomas." (PMID 33750776, 2021). "Although targeting BRAF is highly effective in tumor types carrying mutant BRAF (i.e., melanoma), rapid resistance against BRAF inhibitors (especially when given as monotherapy) frequently occurs." (PMID 33916289, 2021). "Exposure of melanoma cells to BRAF and MEK inhibitors has been shown to slow growth and result in increased expression of NGFR and ECM and focal adhesion genes." (PMID 33438577, 2021). "During treatment, when melanoma cells bypass BRAF inhibition, MITF expression inversely correlates with AXL, a TKRs family member." (PMID 33922284, 2021). "That suggests that combination of EGFR and BRAF inhibitor shows synergistic effects in BRAF-mutant human melanoma in preclinical model." (PMID 34809598, 2021). "This has led to the development of drugs targeting mutant BRAF as a strategy for directly targeting melanoma growth." (PMID 33549048, 2021). "Next, using data from a 451HLu human melanoma cell line treated with BRAF inhibitors (BRAFi), we evaluated Beyondcell’s ability to identify drug-resistant cellular populations and to propose drug treatments." (PMID 34911571, 2021). "Usp9x knockdown, as well as inhibition with DUB inhibitor, G9, blocked SOX2 expression, suppressed in vitro colony growth, and induced apoptosis of BRAF-mutant melanoma cells." (PMID 33613844, 2021).
melanoma (continued). "Following its discovery, several therapeutic approaches targeting BRAF have been studied, first in melanoma and then in other cancers." (PMID 35155453, 2021). "We also show that protein levels of TF SOX2 were induced dose dependent in mutant BRAF melanoma cell lines, A375, treated with BRAFi, vemurafenib, and MEKi, PD0325901." (PMID 33613844, 2021). "Treatment of BRAF V600E melanoma patients with BRAF inhibitors, such as PLX4032, leads to systematic resistance and metastasis relapse." (PMID 33431809, 2021). "As a result, melanomas have been classified into four distinct genetic subsets based on the molecular signature (BRAF mutant, NRAS mutant, NF1 mutant, and triple negative)." (PMID 34831002, 2021). "In this context, a preclinical study evidenced that such a combination attenuates cell migration and in vivo colonization of BRAF-mutant melanoma cells." (PMID 33918490, 2021). "When it comes to targeted therapeutics, melanoma persister cells are generally derived by co-treatment with BRAF/MEK inhibitors, making it unclear how persister metabolism is affected by each drug, individually." (PMID 34822435, 2021). "Among nine patients with somatic mutation testing performed on melanoma tumors, there were four NRAS Q61R mutations, three BRAF V600E mutations, and one loss-of-function NF1 mutation." (PMID 34262818, 2021). "In melanoma, high levels of BRAF‐V600E concomitantly trigger a senescent‐like phenotype and autophagy through mTOR downregulation; inhibiting autophagy allowed cells to resume proliferation." (PMID 34355491, 2021). "Another prevalent BRAF mutation at the same residue, accounting for 10-30% of all BRAFV600-mutated melanomas, is V600K mutation (BRAF-V600K) in which the valine residue (V) is replaced by a lysine (K) through a two nucleotides substitution (GTG to AAG)." (PMID 34123788, 2021). "Our findings indicate that both the expression and proper trafficking are essential for the antimigratory activity of the PMCA4b pump in BRAF mutant melanoma cells." (PMID 33802790, 2021). "Collectively, we proposed that the ERK1/2-MNK1 axis is required for bilirubin-induced reversal of growth inhibition and apoptosis induction in BRAF mutant melanoma following vemurafenib treatment." (PMID 34222023, 2021). "Dimeric aminobenzimidazole (diABZI) is another STING agonist that promotes tumor cell death in melanoma in combination with BRAF inhibitors." (PMID 34830754, 2021). "Previous experimental work has shown that drug combinations, drug doses and treatment schedules all impact the evolution of drug-resistant tumour subclones in melanoma when the tumours are subjected to inhibitors that target the BRAF-MEK-ERK pathway." (PMID 34621046, 2021). "One study showed increased sensitivities to the MEK inhibitor selumetinib and BRAF inhibitor vemurafenib in BRAF-mutant melanoma with low-pAKT expression." (PMID 33807778, 2021). "In keeping with this, inhibition of the oncogenic BRAF protein has resulted in significant response rates in BRAF mutant melanomas." (PMID 34503064, 2021). "Among patients receiving BRAF ± MEKi therapy, 37 patients (15 female, 22 male) developed a CR (8.0% of all advanced melanoma patients receiving BRAF ± MEKi therapy) and were enrolled into this retrospective study." (PMID 34065877, 2021). "To understand the molecular mechanisms adopted by miR-181a/b to regulate the sensitivity and resistance to target therapies in melanoma, we performed a transcriptome profiling of melanoma BRAF-inhibitor sensitive and resistant cell lines." (PMID 33670365, 2021). "For example, in humans, targeting BRAF with the agent vemurafenib works more effectively in melanoma than in other cancer types." (PMID 33834049, 2021). "BRAF-inhibitor resistant melanomas were shown to upregulate NRF2-mediated antioxidant response to maintain cell survival." (PMID 33451139, 2021).
melanoma (continued). "The aim of our study was to evaluate the prognostic value of BRAF and NRAS mutation, evaluated in everyday clinical practice, in relation to the most important prognostic parameters, especially, the SLN status of melanoma patients." (PMID 34209415, 2021). "Surprisingly, in contrast to the efficacy observed in BRAF-mutant melanoma, BRAF inhibitors were found to activate ERK and stimulate growth of RAS-mutant cancers by an effect known as the RAF inhibitor paradox." (PMID 34200676, 2021). "Metabolic reprogramming is observed in melanoma following standard-of-care BRAF/MEK inhibition and is involved in both therapeutic response and resistance." (PMID 33572972, 2021). "In conclusion, in human melanoma, the loss of BRN2 is preferentially associated with BRAF mutation together with PTEN loss." (PMID 34140478, 2021). "BRAF/MEK inhibition reprograms metabolism in melanoma, involving a decrease in glycolysis and a compensatory increase in oxidative phosphorylation that is mediated at least in part by a MITF-PGC1A pathway." (PMID 33572972, 2021). "Consistent with NSCLC patient data sets, almost half of melanoma patients possess activating mutations in the MAPK pathway, including KRAS and BRAF." (PMID 33972557, 2021). "Of note, bilirubin failed to reverse the expression of PARP cleavage triggered by vemurafenib after the depletion of MNK1 by siRNAs in BRAF mutant melanoma cells." (PMID 34222023, 2021). "Ribociclib was evaluated with Binimetinib (NRAS/MEK inhibitor) or Encorafenib (BRAF inhibitor) in two different Phase I/II clinical trials in advanced NRAS and BRAF mutant melanoma." (PMID 34071228, 2021). "Consequent to tumor heterogeneity in advanced melanoma, resistances against therapies for BRAF and MEK inhibitors develop." (PMID 34768746, 2021). "Several years ago, BRAF inhibitors such as vemurafenib, dabrafenib, and encorafenib revolutionized the treatment of melanoma, nowadays given in combination with MEK inhibitors like cobimetinib, trametinib and binimetinib." (PMID 34768746, 2021). "Pharmacologic inhibition of BRAFV600E signaling induced autophagy in BRAFi-resistant melanoma cell lines significantly more than in BRAF-sensitive cell lines." (PMID 34298710, 2021). "Although progress has been made in targeting melanoma with pre-requisite genotypes using small molecule inhibitors such as BRAF/MEK inhibitors, most relapse after 6 to 9 months as the majority will develop drug resistance." (PMID 34572747, 2021). "Unlike BRAFi, which are designed to selectively inhibit oncogenic BRAF in melanoma, MEK inhibition (MEKi) is designed to target wild type MEK, which is universal across melanoma and other cell types." (PMID 34025662, 2021). "Melanoma patients with mutant BRAF expressing tumors can be treated with BRAF and MEK kinase inhibitors with substantial clinical activity but is limited in duration." (PMID 33613844, 2021). "In BRAF mutant melanoma, PTEN loss activates MAPK and PI3K signalling through the suppression of BIM-mediated apoptosis, conferring resistance to BRAF inhibitors." (PMID 34066022, 2021). "Additional research suggests that resistance to MEK inhibitors and other melanoma therapies involved in this pathway, including BRAF inhibitors, are complex and intricately related." (PMID 33807778, 2021). "In BRAF‐mutant melanoma, ZEB1 is sufficient and only partly compensated by TWIST to promote an undifferentiated p75high neural crest stem cell‐like state that is characterized by resistance to MAPK and BRAF inhibitors." (PMID 34459003, 2021). "To examine the initial response to dabrafenib, we treated BRAFV600E melanoma lines with the BRAF inhibitor dabrafenib and found that MAPK signalling and proliferation were initially repressed but rebounded within 3 days of treatment." (PMID 33741929, 2021). "All NRAS mutant melanoma cell lines in our panel were less sensitive to trametinib treatment than the BRAF mutant SK-Mel-19 cell line." (PMID 33921974, 2021).